RN7SKP8 (RN7SK pseudogene 8)
Gene: Miscellaneous RNA gene on chromosome 13 (98,203,835 to 98,204,192, reverse strand). Ensembl gene ENSG00000222969.
Homologues: Orthologues: chimpanzee 7SK (98% identical), mouse Gm55378 (49% identical). Paralogues in human: RN7SKP176 (68% identical), 7SK (67% identical), RN7SKP180 (67% identical), RN7SKP9 (66% identical), RN7SKP30 (66% identical), RN7SKP47 (65% identical), RN7SKP255 (65% identical), RN7SKP217 (65% identical), RN7SKP48 (65% identical), RN7SKP79 (65% identical), RN7SKP173 (64% identical), RN7SKP189 (64% identical), and 284 more.